B3GAT1-DT (B3GAT1 divergent transcript)
Synonyms: LOC283177; AP004608.1
Gene: Long non-coding RNA gene on chromosome 11 (134,412,267 to 134,532,225, forward strand). Ensembl gene ENSG00000255545.
Diseases named in the same sentence as B3GAT1-DT in open-access papers:
B3GAT1-DT is named in the same sentence as 1 disease in open-access papers, as found by Europe PMC text mining. Sharing a sentence is not in itself a finding about the gene and the disease.
B3GAT1-DT shares sentences with these, for which no sentence is quoted: prostate carcinoma (2 papers).